EGFR (epidermal growth factor receptor)
Diseases named in the same sentence as EGFR in open-access papers (continued):
Sharing a sentence is not in itself a finding about the gene and the disease.
tumor (continued). "Immunohistochemistry showed strong positive expression of PD-L1 (> 50% of tumor cells) with no EGFR or ALK genomic tumor aberrations." (PMID 30832704, 2019). "Moreover, we examined combination therapy using an EGFR inhibitor and a VEGFR inhibitor targeting both tumor cells and endothelial cells." (PMID 31074391, 2019). "To understand how TNuF or the combined treatment negatively regulates neoplastic processes and angiogenesis, we set out to examine possible pathways that regulate productions of epidermal growth factor receptor (EGFR), vascular endothelial growth factor (VEGF), HIF-1α and CD31 in tumor tissues." (PMID 31426614, 2019). "Our findings elucidate MYST1 as a tumor promoter in GBM and an EGFR activator, and may be a potential drug target for GBM treatment." (PMID 31691527, 2019). "These allow to study the specificity of EGFR-targeted PDT better than, for example, transplantation of patient-derived tumor cells in mice, where the species difference can contribute to differential response of (human) tumor and (mouse) wildtype cells." (PMID 31694307, 2019). "Using human ex-vivo GBM slice cultures, it has been found that GBM tumours that have their EGFR gene amplified are more invasive than those that have not, suggesting that EGF signalling stimulates GBM cell migration." (PMID 31601895, 2019). "Compared to gefitinib treatment, BEZ235 or PD0332991 could inhibit tumor growth, and the combination of gefitinib, BEZ235 and PD0332991 even dramatically suppressed tumor growth in the EGFR-TKI resistant xenografts of PC9/ER." (PMID 31801598, 2019). "In contrast to erlotinib, gefitinib exhibits anti-tumour activity independent of the expression level of EGFR." (PMID 31616641, 2019). "Among the tumor-related genes, the top amplified genes included ERBB2 (17q21), MYC (8q24), GNAS (20q13), EGFR (7p11), ZNF217 (20q13), CCNE1(19q12), NCOA3 (20q13), and CDK6 (7q21), and the most frequently deleted genes were CDKN2A (9p21), CDKN2B (9p21), KIT (4q12), SMAD4 (18q21), and FGFR1 (8p12)." (PMID 31541076, 2019). "In a mouse subcutaneous tumor model, EGFR-targeted nanocells were found to successfully inhibit tumor cell growth and reduce tumor volume compared with nontargeted nanocells." (PMID 31349643, 2019). "Interestingly, using SRM as a reporting method, HER3 and possibly EGFR levels appear to linearly correlate with HER2 levels, possibly indicative for the presence of HER2 heterodimers in the tumor." (PMID 30897176, 2019). "Wildtype organoids grown from tumor-adjacent normal tissues showed lower EGFR expression levels than their tumor counterparts, and were not affected by PDT." (PMID 31694307, 2019). "This suggests that c-Met signaling might already play a role in tumor growth before EGFR-TKI treatment, not only acting as a resistance mechanism against EGFR-TKIs." (PMID 31817278, 2019). "Finally, neratinib significantly inhibited tumor growth in vivo in xenograft models overexpressing HER2 (3T3/neu and BT474) and EGFR (SKOV-3 and A431)." (PMID 31141894, 2019). "Our evidence for EGFR feedback activation in MG63 and U2OS cells post-LY5 treatment may explain the limited repression of tumor growth upon STAT3 dephosphorylation." (PMID 31422383, 2019). "Similar to the result in vitro, EGFR inhibitors failed to induce those residual tumor cells apoptosis." (PMID 31316001, 2019). "In addition, EGFR-TKIs can potentiate the induction of MHC class I and II molecules in response to IFN-γ and enhance T cell-mediated tumor killing." (PMID 31526368, 2019).
tumor (continued). "The patient’s tumor sample was found to be BRAF V600E mutated without other mutation (KRAS, EGFR [epidermal growth factor receptor], ALK, c-Kit)." (PMID 31340860, 2019). "FC-TPP11 also promotes the efficacy of co-administered doxorubicin, and its coupling to cetuximab (Erbitux), a monoclonal antibody against EGFR, significantly improves its tumor penetration and accumulation without compromising its serum half-life." (PMID 30717262, 2019). "They reported that patients with EGFR mutation showed a lack of T-cell infiltration and shrinking proportion of PD-L1+/CD8+ TIL, suggesting an uninflamed tumor microenvironment." (PMID 31722672, 2019). "The interaction between the extracellular domain of NRP1 and epidermal growth factor receptor (EGF) leads to the stimulation of tumor cells’ response to EGF and transforming growth factor-α (TGF-α), which may contribute to EGFR activation." (PMID 30871059, 2019). "Accordingly, NOX1/ROS signaling may contribute to the activation of EGFR signaling by suppressing PTP functions, which may be a major tumor-promoting mechanism of NOX1/ROS signaling." (PMID 30700829, 2019). "Here, we first screened the EGFR and HER3 expression in primary and metastatic NSCLC tumor tissue." (PMID 31092882, 2019). "After correcting for nonspecific binding signals, EGFR surface+ cell populations between tumor and cultured cells were comparable, while a 57-fold increase in mean PRL3 surface+ cell population was noted in tumors compared to cultured cells." (PMID 31171773, 2019). "FISH analyses on the paired GSC xenografts demonstrated amplified and non-amplified EGFR in pre- and post-dacomitinib tumours, respectively, which reflected the differential EGFR expression levels on immunohistochemistry." (PMID 30644426, 2019). "In an HCC827 EGFR-mutant NSCLC xenograft mouse model, combination treatment with DS-1205b and erlotinib significantly delayed the onset of tumor resistance compared to erlotinib monotherapy, and DS-1205b restored the antitumor activity of erlotinib in erlotinib-resistant tumors." (PMID 31497246, 2019). "Recently, asporin expression was also shown to be dysregulated in tumor tissues and positively or negatively correlated with tumor proliferation, migration, invasion, and patient prognosis by regulating different signaling pathways, including the TGF-β, EGFR, and CD44 pathway." (PMID 31608236, 2019). "Consequently, to multiple verify the inhibitory effect of the L14e on the EGFR signaling pathway, we detect the levels of VEGF secreted by tumor cells." (PMID 31296849, 2019). "In the rat breast precancerous lesions model, high and low dose RYNXC could also significantly reduce genes and proteins expression of ESR1, PGR, PTGS2, EGFR, and Src." (PMID 30906412, 2019). "Regarding biological agents, a recent meta-analysis concluded that the addition of an anti-EGFR antibody to chemotherapy markedly increases the response and R0 hepatectomy rate, whereas the addition of BV exhibits no benefit in tumor regression." (PMID 30612267, 2019). "PD-L1 expression in a tumor sample obtained by bronchoscopy was negative, and the status of ROS1 and ALK rearrangements and EGFR mutation were non-informative." (PMID 30986912, 2019). "Initial tumor stage, gender, smoking status, and the number of prior EGFR TKIs had no significant impact on treatment outcomes." (PMID 32914023, 2019). "For instance, EGFR is expressed in most CRCs and its expression level is a marker of poor prognosis, but the clinical activity of anti-EGFR antibodies does not correlate with its tumour protein level." (PMID 31091767, 2019).
tumor (continued). "High-levels of EGFR amplification were detected by comparing the read coverage of each sample with a baseline performed on 12 formalin-fixed, paraffin-embedded (FFPE), non-tumor samples." (PMID 31167453, 2019). "Therefore, we mainly tested the anti-tumor effects of four representative agents in HMSM, including anti-WNT5A antibody, PLX3997, Anti-IL-2 antibody (IL-2 neutralization), and EGFR inhibitor." (PMID 31504033, 2019). "Interestingly, anti-EGFR sensitization of IGORV-1 for 7 days resulted in significantly enhanced NK cytotoxicity and increased NK-specific tumor cell lysis in the presence of cetuximab." (PMID 31546690, 2019). "Although there was a clear trend, DSS of p16 positive and negative cancers did not statistically differ when stratified by total tumour EGFR levels." (PMID 30630536, 2019). "In the current study, we found that treatment with EGFR siRNA or gefitinib suppressed the growth more significantly in the TF highly expressed HCC cells, suggesting that the levels of TF in tumor cells may influence the effects of EGFR inhibitors." (PMID 30931258, 2019). "In addition, EGFR/EGFRvIII signaling maintains GBM cancer stem cells (CSCs) also called side population (SP) and control tumor progression, recurrence, and resistance to chemoradiation therapy (CRT)." (PMID 31215502, 2019). "Additionally, PCC0208027 acted as an EGFR-TKI by significantly inhibiting EGFR and HER2 phosphorylation levels in tumor tissues." (PMID 30952931, 2019). "In the first, EGFR-Pcn tumor discs were generated from a cross between ap-Gal4,UAS-psqRNAi/CyO;UAS-EGFR,tub-Gal80ts and UAS-CD8:GFP that produces equal numbers of animals with the tumor genotype and non-tumor controls that have the CyO balancer and lack ap-Gal4,UAS-psqRNAi." (PMID 31568500, 2019). "Previous studies have demonstrated that a physical and functional interaction of GPER with steroid (for instance, ERα and MR) and growth factor receptors (for instance, EGFR and IGF-IR) may be involved in cell cycle progression and tumor growth." (PMID 31370872, 2019). "Knockdown of EGFR and AJAP1 promoted tumor growth and β-catenin nuclear expression." (PMID 31171012, 2019). "In tumor samples from EGFR-mut NSCLC patients, the levels of non-mitotic pH3 were significantly elevated after progression to TKIs." (PMID 31000705, 2019). "Human cSCC samples highly express EGFR, whereas GLI1 is only expressed in distinct tumor areas." (PMID 31867038, 2019). "Since the primary antibody used to stain EGFR was human specific, it is unlikely that absence of EGFR in tumor cells in xenografts is due to technical issues or antibody clone." (PMID 31732509, 2019). "In October 2016, FDA has approved pembrolizumab for the first-line treatment of patients with metastatic NSCLC whose tumors have high PD-L1 expression (≥50% PD-L1 expression) with no EGFR or ALK genomic tumor aberrations based on the study of KEYNOTE-024." (PMID 31205619, 2019). "EGFR-FITC-SiO2-NPs were occasionally found in the tumor, whereas no FITC-SiO2-NPs were found in the CAM or the tumor." (PMID 31561451, 2019). "In addition to the EGFR system, IL8, a cytokine well studied for its role in promoting tumor angiogenesis, cell motility, and invasion, has been described as an activator of bone destruction in metastatic and MM bone disease." (PMID 30621731, 2019). "Furthermore, canine NK lymphocytes are capable of ADCC function mediated by trastuzumab and cetuximab even in tumor cells with very low expression of HER-2 and EGFR." (PMID 31610784, 2019). "The median PFS of patients with tumor tissue positive or negative for AXL expression before EGFR‐TKI treatment was 14.3 and 11.9 months, respectively, whereas the corresponding values for OS were 40.5 and 32.1 months, respectively." (PMID 31419057, 2019).
tumor (continued). "For patients lacking matched tumor tissues for NGS test in cohort 2, the liquid biopsy results were compared to the initial amplification-refractory mutation system (ARMS) test of EGFR 19del and L858R mutations on diagnostic samples." (PMID 31534501, 2019). "On the other side, transactivation of various growth factor receptors, such as epidermal growth factor receptor (EGFR) by GPCRs, has been observed in multiple cellular model systems, therefore illustrating the plausible role of GPCR in tumor tropism by means of receptor transactivation." (PMID 31555593, 2019). "The evidence suggests that paracrine factors secreted from the EGFR-TKI–resistant CAFs mitigate the EGFR-TKI–mediated blockade of pEGFR and pMAPK in cocultured tumor cells, regardless of their EGFR mutational status." (PMID 31014370, 2019). "This is because constitutively activated RAS downstream signaling can activate multiple processes involved in tumor progression without the influence of EGFR and related receptor kinases." (PMID 31771279, 2019). "Similar to lapatinib-stimulation of HER2 levels only in castrated mice bearing 22Rv1 tumours, we saw increased EGFR/HER2 (but not EGFR/ErbB3) heterodimerisation with lapatinib only in CRPC cells in CSS." (PMID 31209328, 2019). "Although oncogenic mutations affect tumor cell metabolism, the relationship of PD-L1 and HK2 expression was not affected by EGFR mutation status in NSCLCs." (PMID 31718692, 2019). "Comparative trials and meta-analyses suggest that anti-EGFR agents may be more effective in terms of tumour shrinkage than bevacizumab for RAS WT patients, especially in left-sided primary tumours." (PMID 30565083, 2019). "Targeting single genetic alterations, such as EGFR-mutants does not seem sufficient to ensure long-lasting or even curative tumor regressions." (PMID 31266248, 2019). "Other possible signatures of recurrent tumour resistance in this GBM cohort included CNV gains in the genes (chromosome), BRCA2 (Chr13), GNAS (Guanine nucleotide-binding protein G(s) subunit alpha; Chr20), and EGFR (Chr7)." (PMID 32082376, 2019). "The heterogeneous but co-existing distribution of these EGFR, MET, and PDGFRA gene amplifications suggests that glioblastoma may undergo a dynamic evolution during tumour progression that creates diversity within a single mass." (PMID 30736342, 2019). "Furthermore, asporin is also positively or negatively correlated with tumor proliferation, migration, invasion, and patient prognosis through its regulation of different signaling pathways, including the TGF-β, EGFR, and CD44 pathways." (PMID 31608236, 2019). "Although the dual combination of EGFR and HA targeting has not yet been widely studied, it has appeared as an efficacious way for tumor-targeted therapy to decrease the uncertainty of single targeting." (PMID 31754382, 2019). "Of the 29 candidate compounds tested, EE02 showed remarkable inhibition of the growth of tumor cells with high expression of EGFR and Eps8 and promoted apoptosis, while did not significantly inhibit and promote apoptosis in normal cell lines." (PMID 31118055, 2019). "Twelve cfDNAs carried the same EGFR mutation found in tumor tissue (EGFR+), whereas the remaining 12 samples were EGFR mutation negative (EGFR−)." (PMID 31861832, 2019). "We aim to determine whether combining PDT using ALA-protoporphyrin IX (PpIX) with a liposomal formulation of the clinical epidermal growth factor receptor (EGFR) inhibitor, lapatinib, would increase the anti-tumour PDT efficacy." (PMID 31847378, 2019). "By influencing the tumor microenvironment and the immune system, blocking the expression of COX-2 and the proto-oncogene c-FOS and interfering with the EGF/EGFR pathway, they are able to reduce inflammation, inhibit tumor cell growth, induce apoptosis, and cause autophagy." (PMID 30987191, 2019).
tumor (continued). "However, a major limitation of these approaches is that tumor cells eventually develop resistance and AXL activation is among the mechanisms of acquired resistance to EGFR inhibition in NSCLC treatment." (PMID 31729427, 2019). "ANXA1, a tumor suppressor in HNSCC, regulates EGFR activity and exosomal phospho-EGFR release, revealing that exosomal EGFR and phospho-EGFR may be prognostic biomarkers in HNSCC." (PMID 31620359, 2019). "Besides, SPRY2 has also been identified as a crucial negative regulator of multiple tumor-driving signaling pathways, such as ERK1/2, Smad2 and EGFR pathways." (PMID 30837325, 2019). "Most importantly, activation of autophagy can induce either cancer cell chemoresistance (when initiated via EGFR signaling for example) or autophagic cell death (e.g., when initiated by β-catenin, AKT or Ras signaling), depending on the tumor type and treatment." (PMID 30646599, 2019). "Different tumor therapies targeting EGFR via antibodies or small molecules often do not have response rates as successful as expected." (PMID 31438847, 2019). "Additional reports explored the activity of CAR NK cells in tumor xenograft models, including CAR targets of hematological cancers (e.g., CD19, CD20, CD138, and CS-1) and solid tumors (e.g., HER2, EpCam, GD2, GPA7, PSCA, EGFR, and EGFRvIII)." (PMID 31212634, 2019). "Therefore, 213Bi-anti-EGFR-MAb treatment had resulted in eradication of 99.98% (EJ28Luc) and 99.99% (LN18) of tumor cells, respectively." (PMID 31165773, 2019). "Our results indicate that AURKB is activated in NSCLC tumor cells with acquired resistance to EGFR TKIs and can be a therapeutic target in absence of resistance mutations." (PMID 31000705, 2019). "Furthermore, blocking both EGFR/HER2 signaling and cell cycle transition through the combinatory regimen of anti-EGFR treatment and CDK4/6 inhibitors successfully hindered TNBC tumor progression." (PMID 31253784, 2019). "Additionally, MK2206 appears to synergise with EGFR/HER2 inhibition, and preliminary anti-tumour activity of MK2206 in combination with trastuzumab has been documented." (PMID 31540244, 2019). "Patients with a L8585R-positive tumor had a significantly better mPFS (12.6 vs. 6.3 months, P = 0.03) and a trend of a longer mOS (28.9 vs. 25.6 months) if EGFR-TKI was the first-line rather than the later-line treatment." (PMID 31870097, 2019). "In this study we extended this observation to NSCLC and particularly to AdC and showed that p65BTK levels were significantly higher in EGFR-wt tumours from never-smoker patients and in tumour with metastasis at distant nodal stations." (PMID 31200752, 2019). "A phase II study evaluating the use of cetuximab, an antibody which binds the epidermal growth factor receptor (EGFR) expressed on tumor cells, found no improvement in survival, despite prior apparent antitumoral effects in mice." (PMID 30863442, 2019). "It was also reduced in EGFR/KRAS wild-type tumours, although not significantly (normalised expression level of 1.7; p > 0.05)." (PMID 30953094, 2019). "Examples of tumor target antigens include CD19, EpCAM, Her2/neu, EGFR, CEA, and more." (PMID 31488104, 2019). "It is known that afatinib resistant NCI-H1975 tumor clones showed lower PTEN expression levels than control clones, suggesting the decreased PTEN expression might contribute to the resistance to EGFR-TKI therapy." (PMID 31060329, 2019). "As immune response related gene sets were characteristically enriched in EGFR-MUT cases, we investigated whether this enrichment trait was correlated with increased tumor infiltrated immune cells (TIIC)." (PMID 31801484, 2019). "DTLL's tailored internalization into tumor parenchyma cells after specifically binding to EGFR/HER2 might contribute to blockage of their targeting pathways—the PI3K/AKT/mTOR signaling and PD‐L1‐medicated tumor escape from immunosurveillance." (PMID 30681288, 2019).